TNF (tumor necrosis factor)
Diseases named in the same sentence as TNF in open-access papers (continued):
Sharing a sentence is not in itself a finding about the gene and the disease.
cancer (continued). "TNF-α can be an antineoplastic and antiangiogenic agent which stimulates the immune system to fight cancer cells." (PMID 30518097, 2018). "It has been well established that TNF-α induces the production of matrix metalloproteinases (MMPs) by carcinoma cells originating from various tissues, and these MMPs facilitate cancer cell invasion and metastasis." (PMID 30544870, 2018). "In contrast, we identified a significant decrease in the frequency of TNF producers in cancer septic mice relative to previously healthy septic controls." (PMID 29338031, 2018). "The strength of cancer cell adherence has been recognized as being determined by local inflammation, in particular by the activity of IL-1β and TNFα, and by oxidative stress." (PMID 28956065, 2018). "TNFα and NF-κB signaling promote cancer progression by facilitating cell migration, invasion, and metastasis." (PMID 30591653, 2018). "Tumor necrosis factor (TNF)-α belonging to the TNF/TNF receptor cytokine superfamily can be found in plasma or serum of healthy people, as well as some cancer patients." (PMID 29867530, 2018). "TNF-α is frequently detected in biopsies from human cancer, produced by either epithelial tumor or stromal cells." (PMID 29593647, 2018). "Chronic inflammation as mediated by interleukin-6 (IL-6) and tumor necrosis factor alpha (TNF-α) has been widely investigated as an important regulator of fat wasting in cancer cachexia." (PMID 29338749, 2018). "TH1 cells secrete IFN-γ, IL-2 and TNF-α and thereby activate the ‘cellular immunity’ pathway which is responsible for protection against viruses, cancer and intracellular pathogens." (PMID 30229370, 2018). "To confirm the role of inflammatory signals in M1-induced EMT, we neutralized IL-6, IL-1β, and TNFα in M1-treated A549 cancer cells and examined the expression of EMT markers." (PMID 30218063, 2018). "TNF-α has been shown to deteriorate malignant phenotypes of cancer cells, including cell proliferation, migration, epithelial-mesenchymal transition, and productivity of cytokines and growth factors." (PMID 30544870, 2018). "Among them there were NF-kappa B, TNF, Pathways in cancer, Phagosome, HIF-1, VEGF, Chemokine and other signaling pathways." (PMID 30185153, 2018). "Several reports have also indicated that inhibition of autophagy increases the sensitivity of human cancer cells to the tumor necrosis factor (TNF)-related apoptosis-inducing ligand (TRAIL)." (PMID 29513749, 2018). "In the new era of cancer immunotherapy, a promising research direction is augmentation of endogenous TNF-alpha activity through removal of its soluble receptors." (PMID 30170620, 2018). "Certain types of cancer can promote the up-regulation of pro-inflammatory cytokines including interleukin-6 (IL-6), tumor necrosis factor-α (TNFα), and interferon-γ, many of which are anorexigenic and/or proteolytic." (PMID 30460194, 2018). "It was nonetheless enhanced (from 17% up to 28%) with the addition of a disturbing agent (TNF-α or cancer cells) as suggested by the EPR theory." (PMID 30311803, 2018). "The other enriched categories comprised items related to cancer development, which included TNF signaling pathway (four genes), pathways in cancer (six genes) and PI3K–Akt signaling pathway (five genes)." (PMID 29744300, 2018). "Our previous results demonstrated that neutrophils promote cancer invasion through a TNFα- dependent pathway and our data now shows a significant increase in neutrophils and TNFα in the saliva of cancer patients." (PMID 30018735, 2018). "We also describe new targets in immunotherapy of cancer, emphasizing on the putative suppressive effect of TNF in antitumor immunity and of the interest of blocking TNFR2 to regulate the Treg compartment." (PMID 29593717, 2018).
cancer (continued). "The property of TNF‐α in promoting the death of cancer cell suggests TNF‐α to be a potential cancer therapeutic drug." (PMID 29632814, 2018). "Restoration of E-cadherin and downregulation of N-cadherin were noted after TNFα neutralization, suggesting that TNFα plays a predominant role in M1-induced EMT of cancer cells." (PMID 30218063, 2018). "TNF-α was also reported to have a carcinogenesis-promoting effect as serum TNF-α concentration is elevated in patients with advanced cancer and correlates inversely with prognosis after surgery." (PMID 30301191, 2018). "The EGFR-mediated suppression of IFNγ/TNFα mediated amplification of the T-cell infiltrate in these cancers bears strong similarities with observations in skin inflammation disorders." (PMID 30192802, 2018). "It is strongly rationalized to develop a combinational therapy with anti-PD-1/PD-L1 and anti-TNF-α in cancer patients." (PMID 30547012, 2018). "Smac mimetics when tested as single agents can induce apoptosis in cancer cells via a TNFα autocrine mechanism, but only a small subset of cancer cells response to Smac mimetics and there is no biomarker to predict the response." (PMID 29946223, 2018). "Patients with multiple advanced cancers have elevated TNF-α expression in biopsies and in the plasma." (PMID 29559745, 2018). "Chronic inflammation, mediated by cytokines such as tumor necrosis factor alpha (TNF-α) and interleukin-6 (IL-6), has been reported to promote cancer cachexia." (PMID 29338749, 2018). "USP4 has previously been confirmed to target TRAF2 and TRAF6 for deubiquitination and it has been established that USP4 inhibits TNFα-induced cancer cell migration." (PMID 30194441, 2018). "Trastuzumab, a recombinant humanized IgG1 antibody against the extracellular domain of HER2, blocks the HER2 receptor on the cell surface, sensitizes cancer cells to the tumor necrosis factor (TNF) and inhibits neoangiogenesis." (PMID 29721214, 2018). "Anyway, in the case cancer is found during anti-TNF treatment, it is advisable to interrupt the treatment until the cancer is under control." (PMID 29751683, 2018). "Co-injection of M2 macrophages with A549 increased the pulmonary colonization of cancer cells, and the effect was more significant in TNFα-primed cancer cells." (PMID 30218063, 2018). "Elevated iron in cancer cells and pericarcinomatous compartments protect cancer cells from natural killer cell cytolysis by upregulating ferritin expression and by antagonizing tumor necrosis factor (TNFα)- and NO-induced cytotoxicity." (PMID 30591630, 2018). "Within the brain, cytokines including IL-6 and TNF-α are typically tasked with promoting neurogenesis and offering neural trophic support; however, overactive immune pathways seen in cancer are thought to lead to dysregulation of these processes." (PMID 30042700, 2018). "Increased interleukin-1, 6, 10, and tumor necrosis factor-α (TNF-α) levels will initiate the process of cancer development, followed by three steps." (PMID 29474889, 2018). "This corroborated a role for TNF as a modulator of the circadian clock in our cellular model of a cancer type involving cells of the immune system." (PMID 30065253, 2018). "On the other hand, use of monoclonal antibodies against pro-inflammatory cytokines (TNF-alpha and IL-6) in different cancers led to sporadic disease stabilization, thus suggesting the poor efficiency of such a therapeutic strategy." (PMID 29558948, 2018). "It was first shown that ectopic expression of PML converts cancer cells from TNF-resistant to TNFα-sensitive cell death, in part by sequestering the pro-survival factor NFκB to PML NBs." (PMID 29416846, 2018). "Inflammation triggered both by hepatitis and cancer progression has been shown to up-regulate TNFα, a pro-inflammatory cytokine, in Md2-knockout mice." (PMID 30060453, 2018).
cancer (continued). "The study analyzed an Ad carrying the tumor necrosis factor (TNF)-related apoptosis-inducing ligand (TRAIL) that preferentially induced apoptosis in radio-resistant cancer cells." (PMID 29534501, 2018). "As expected, plasma levels of IL-8, IL-6, TNFα, IL-1β, and G-CSF were all significantly higher in cancer patients compared to healthy individuals." (PMID 29324871, 2018). "These growth factors synergize with the proinflammatory factor, TNF-α to act on the cancer cells and accelerate the secretion of osteoclast-activating factors." (PMID 29416737, 2018). "TNF-α is a multifunctional cytokine that modulates various aspects of cancer cell phenotypes, such as cell proliferation, migration, invasion, and metastatic potential, in addition to causing the death of cancer cells." (PMID 30544870, 2018). "This implicates tightly controlled feedback mechanisms of both TNFα-activated pathways to prevent cancer." (PMID 30591653, 2018). "On the other hand, higher expression of HRAS, NRAS, APC, HFE, MMP9, and a high enrichment of MAPK/RAS, NFKB, and TNF signaling pathways are all evident in HLE cells as often seen in cancer." (PMID 30176945, 2018). "Accordingly, we will discuss below the cellular effects of TNF-alpha in various immunological and cancer systems." (PMID 30170620, 2018). "In agreement, TNFα-mediated CD of carcinoma cells was reduced after a brief pretreatment with a sulytic dose of complement." (PMID 29527209, 2018). "We then utilized the reconstituted artificial mesothelium, which was composed of a monolayer of mesothelial cells cultured on a Matrigel layer in a Boyden chamber system, to examine the effects of TNF-α on carcinoma cell invasion." (PMID 30544870, 2018). "Tumor necrosis factor alpha (TNF-a), a major pro-inflammatory cytokine, shows increased expression within the gallbladder mucosa from hyperplasia to carcinoma." (PMID 29914418, 2018). "The TNF-α treatment of these cells resulted in the induction of MMP-9 secretion not only from MKN1 carcinoma cells but also from mesothelial cells." (PMID 30544870, 2018). "IL-6 and TNF-α are two proinflammatory cytokines that well recognized to have close relationship with promotion and progression of cancer." (PMID 29100404, 2017). "For instance, a mix of TGF‐β, IFN‐α, and TNF‐α can be used to induce EMT‐like changes in human cancer cell lines in vitro." (PMID 28599100, 2017). "TNF-α was first identified for its ability to induce rapid hemorrhagic necrosis of experimental cancers." (PMID 29069789, 2017). "As a result, TNF-α drove quiescent cancer cells out of G0/G1 phase, entering treatment sensitive proliferating phases." (PMID 28127258, 2017). "Some studies have reported that various biomarkers, such as TNF-alpha, interleukin (IL)-1 beta, IL-6, IL-2, CRP, etc., are associated with cancer-related fatigue, although the results of these studies are not consistent in regarding this issue." (PMID 28679410, 2017). "Recent studies have also shown that TNFα secreted by macrophages play a pivotal role in cancer progression." (PMID 28160574, 2017). "Other inflammatory cytokines, such as IL-1 and TNF-alpha, are also related to the immune-expression increases in cancer patients." (PMID 29259311, 2017). "SMAC-mimetics also increase the sensitivity of some cancer cells to other TNF-related cell death stimuli, such as TRAIL and FasL." (PMID 28607534, 2017). "In cancer cells, SM treatment ideally kills two birds with one stone by simultaneous production of and sensitizing to the effector molecule TNF." (PMID 28771230, 2017). "Cancer-induced TNF-α levels increase corticotrophin-releasing hormone (CRH), which reduces appetite and food intake." (PMID 28785374, 2017). "TAMs accordingly produce multiple growth factors (HGF, EGF, TGF, PDGF, etc.)and inflammatory cytokines (IL‐1β, IL‐6, and TNF‐α) that each can induce EMT in cancer cells." (PMID 28599100, 2017).
cancer (continued). "Herein, our results indicate that TNF or TNFR1 blockade synergizes with anti-PD-1 on anti-cancer immune responses towards solid cancers." (PMID 29273790, 2017). "In the connection between inflammation and cancer development, tumor necrosis factor-alpha (TNF-α) contributes to the tumorigenesis." (PMID 28938560, 2017). "In order to identify the effect of PDTC on lipolysis in cancer cachexia in vitro, we used C26 medium and TNFα to induce lipolysis of mature 3T3-L1 adipocytes." (PMID 29311924, 2017). "RNS, ROS, IL-β, and TNF-α are generated to drive genetic instability and promote cancer-related inflammation." (PMID 28210259, 2017). "Tumor necrosis factor (TNF) is a major inflammatory cytokine that was first identified for its ability to induce rapid hemorrhagic necrosis of cancers." (PMID 28506461, 2017). "COS has functions against cancer and inflammation and is a potential anti-inflammatory drug by activating tumor necrosis factor (TNF) alpha." (PMID 28335413, 2017). "Tumor necrosis factor-α is a major inflammatory cytokine that promotes cancer cell migration and invasion." (PMID 28725636, 2017). "Several pro-inflammatory cytokines, including interleukin-2 (IL2), tumor necrosis factor (TNF) and interferon-α (IFNα), have been approved for clinical use in certain types of cancer." (PMID 28574434, 2017). "Various biological processes are strongly regulated by long-term hypoxia, including basal carcinoma, TNF signaling and cancer pathways." (PMID 29215599, 2017). "But, this study has reported modulatory effect of honey on TNF-α in disease-free models, contrary to cancer models of our study." (PMID 28479926, 2017). "In this study, we examined a selection of monovalent and bivalent IAP antagonists and found that specific bivalent IAP antagonists inhibit the TNF-mediated NF-κB signal transduction pathway in cancer cells." (PMID 28149532, 2017). "Tumor necrosis factor-alpha (TNF-α) is a multifunctional pro-inflammatory cytokine that plays an important role in cancer development." (PMID 28881857, 2017). "Syncytin-1 acted as an important downstream effector in TNF-α-enhanced cancer-endothelial cell fusion." (PMID 28112190, 2017). "TNF is a major inflammatory cytokine that was first identified for its ability to induce rapid hemorrhagic necrosis of cancers." (PMID 28506461, 2017). "With these physiological conditions, we need to establish our own cancer prevention strategy, to reduce TNF-α and IL-1 and inactivate NF-κB." (PMID 28124725, 2017). "Src activation and ICAM-1 phosphorylation in cancer cells can not only be induced by incubation with TNFα but also be blocked by clinically relevant concentrations of lidocaine and ropivacaine." (PMID 29326939, 2017). "TNF has both proinflammatory and immunosuppressive effects depending on the duration and state of the cancer disease; it can overcome the anergic state of T cell receptor-stimulated Tregs but a chronic exposure to TNF leads to an activation of Tregs." (PMID 28427434, 2017). "Cancer is a major clinical implication in which the joint activities of TNFα + TGFβ1 on MSCs are very relevant." (PMID 28553282, 2017). "The aim of this study was to compare serum and peritoneal fluid concentrations of sHLA-G, IL-10 and TNF-alpha in women with selected ovarian pathologies: benign serous cysts, endometrioma and malignant tumors." (PMID 28376925, 2017). "There is evidence in the literature that NFkB and AP-1 signaling contributes to cancer cell migration and invasion through the expression of inflammatory cytokines such as IL-6 and TNF-α." (PMID 28427184, 2017). "TNF is considered to be an effector molecule of the cytotoxic T lymphocytes in anti-cancer immune response." (PMID 29273790, 2017). "MSCs residing in tumors promote cancer development by recruiting macrophages in a TNF-α-treated environment." (PMID 27965469, 2017).
cancer (continued). "Activation of an alternative TNF source attenuated the dependency on SM-induced TNF release for efficient cancer cell killing." (PMID 28771230, 2017). "TNF-α in particular has established roles in cancer progression in bowel, liver, breast and other sites in mice." (PMID 28238104, 2017). "TNFerade is a genetically engineered adenovector with a radiation-inducible promoter that specifically delivers the human TNF-α gene to cancer cells." (PMID 28210259, 2017). "It was also found that cIAP1 can protect cancer cells from the lethal effect of TNF through synergy with the MYC oncogene, thus driving tumorigenesis." (PMID 28529715, 2017). "Induction of the NF-κB and/or JNK pathways by TNF has been intensively analyzed in different cancer cell types and immortalized fibroblasts under various culture conditions." (PMID 28878689, 2017). "A recent study suggest that Lipoxins (LXs) and analogues exert strong analgesic effects on cancer-induced bone pain (CIBP) and suppress the pain associated expression of spinal proinflammatory cytokines (IL-1β and TNF-α)." (PMID 28587280, 2017). "The top pathways these genes are a part of include “pathways in cancer”, “mTOR signaling”, and “TNF signaling”." (PMID 28768481, 2017). "One important finding here is that TNF-α was indispensable for cancer cells migration and invasion by Nur77-elicited inflammation." (PMID 28170411, 2017). "Increased production of lipolytic factors by the adipose tissue, such as TNF-alpha, contributes to the disrupted lipid metabolism and increased lipolysis in cancer cachexia." (PMID 28830524, 2017). "TNF‐α‐induced EMT has been reported in cell lines from multiple other cancer entities: hepatocellular carcinoma, breast cancer, lung cancer, or thyroid cancer (here in combination with IFN‐γ) among others." (PMID 28599100, 2017). "Using a high-content screening of small compounds and FDA-approved drug libraries, we identified the anti-cancer drug Sorafenib tosylate as a potent inhibitor of TNF-dependent necroptosis." (PMID 28661484, 2017). "Inflammatory factor TNF-α is able to promote the growth, invasion, metastasis and lymphangiogenesis in cancer development." (PMID 28938560, 2017). "TNF- alpha is an important inflammatory factor that acts as a master switch in establishing an intricate link between inflammation and cancer." (PMID 29212288, 2017). "In contrast, the majority of studies have tended to demonstrate that autophagy is able to inhibit necroptosis in various systems, such as L929 cells, lymphocytes, or human cancer cells stimulated by TNFα, antigens, or starvation." (PMID 28569199, 2017). "Proinflammation cytokines IFNγ and TNFα in serum were lower than normal reference range in 87 of 130 (66.9%) cancer patients after chemo- and/or radiotherapies." (PMID 28529951, 2017). "We determined that bovine testicular PH-20 increases the susceptibility of murine L929 fibroblasts and prostate LNCaP cancer cells to tumor necrosis factor (TNF or TNF-α) cytotoxicity." (PMID 27845895, 2017). "TNF-α, through a complex regulatory network after activating its receptors, can induce apoptosis or necroptosis, cell growth, invasion or propagation of cancer cells." (PMID 29202842, 2017). "TNFα is one of the important factors involved in the pathogenesis of cancer cachexia; we then used TNFα to induce myotubes atrophy in vitro." (PMID 29311924, 2017). "Our results showed that experimental groups treated with ITF significantly diminished concentration of TNFα compared with cancer-induced experimental group, which showed an important increase of TNFα concentration." (PMID 28293641, 2017). "In TNFα-resistant types of cancer, we showed that TRAIL as another death receptor ligand can mediate SM-induced cell death instead of TNFα." (PMID 28326081, 2017). "This study provides a strong rationale to develop a combination therapy based on the use of anti-PD-1 and anti-TNF in cancer patients." (PMID 29273790, 2017).